JUN (Jun proto-oncogene, AP-1 transcription factor subunit)
Diseases named in the same sentence as JUN in open-access papers (continued):
Sharing a sentence is not in itself a finding about the gene and the disease.
prostate tumors (2 papers, 2024 to 2025). "To clarify the role of AP-1 TFs in PCa progression, we investigated the level of the master factor JUN in tissue microarrays (TMA) of low and high progressive human prostate tumors by immunohistochemistry (IHC)." (PMID 38811984, 2024). "In summary, we propose that levels of JUN and STAT3 potentially orchestrated via PTEN, determine progression stages of human prostate tumors by modulating the immune response through regulation of cytokines and interleukins as identified in the Jun-deficient murine PCa model." (PMID 38811984, 2024). "Given that PPP2R1A and these importins are ubiquitously expressed and that JUN, YAP, MYC, and NF-κB drive many different types of cancer, sphingosine-like drugs should be effective across cancer classes, not just against prostate tumors." (PMID 40588551, 2025).
Rb (2 papers, 2020 to 2022). "Together with JUN, CREBBP is also involved in cell division and cell proliferation, and it is upregulated by the oxidative stress response in retinoblastoma cells." (PMID 32609278, 2020). "However, the identification of JUN, PIK3CA, MAPK1 and UNC5D as hub genes in our study has thrown light on the role of inflammation, cell adhesion and cell proliferation in Rb tumors." (PMID 35359459, 2022).
scleroderma (2 papers, 2016 to 2020). Scleroderma is a rare autoimmune connective tissue disorder characterized by abnormal hardening of the skin and, sometimes, other organs. "We then evaluated how primary dermal fibroblasts from scleroderma and normal skin regulate promoter accessibility of JUN and the hedgehog-associated genes GLI1 and PTCH1 through assay of transposase accessible chromatin sequencing (ATAC-Seq) studies." (PMID 32814713, 2020). "To test if stiffer conditions themselves induce JUN activation, we plated primary scleroderma fibroblasts either on a stiff 70 kDa hydrogel or on a regular polystyrene dish." (PMID 32814713, 2020). "Regarding the role of JUN in human scleroderma, we demonstrate that scleroderma fibroblasts activate JUN on the protein level." (PMID 32814713, 2020). "In accordance with that, the promoter accessibility of JUN is increased in primary human scleroderma fibroblasts compared with normal skin fibroblasts." (PMID 32814713, 2020). "At the end of this part of the study, we demonstrate that stiffer conditions on a hydrogel induced JUN activation, both in scleroderma and pulmonary fibroblasts." (PMID 32814713, 2020). "We first demonstrated in patient samples that scleroderma upregulated transcription factor JUN and increased promoter accessibilities of both JUN and CD47." (PMID 32814713, 2020). "In conclusion, our results with patient sections and human fibroblasts indicated that JUN was activated in human scleroderma both on the protein and on the molecular level, that JUN interacts with the hedgehog pathway, and that stiffer conditions on a hydrogel themselves induce JUN activation." (PMID 32814713, 2020). "In addition, we ran these studies after JUN knockout and under vismodegib to study the effects of JUN and hedgehog inhibition in scleroderma fibroblasts." (PMID 32814713, 2020). "At the beginning, we determined if JUN, CD47, and PD-L1 are commonly upregulated in human scleroderma." (PMID 32814713, 2020). "The ATAC-Seq studies did not answer which mechanism leads to the activation of JUN in scleroderma fibroblasts." (PMID 32814713, 2020). "In accordance with our hypothesis, promoter accessibilities of JUN, GLI1, and PTCH were increased in scleroderma compared with normal skin." (PMID 32814713, 2020).
silicosis (2 papers, 2022 to 2023). Silicosis is a respiratory disease caused by breathing in (inhaling) silica dust. "Moreover, phosphorylation of serine 73 in JUN was enhanced, in which has been previously associated with development of silicosis." (PMID 37040356, 2023).
soft tissue sarcoma (2 papers, 2019 to 2020). A malignant neoplasm arising from muscle tissue, adipose tissue, blood vessels, fibrous tissue, or other supportive tissues excluding the bones. "In approximately 10% of soft-tissue sarcomas, largely irrespective of histological subtype and possibly independent of JUN amplification status, JNK inhibitors that can replace the inhibitory function no longer provided by SERPINB3 may restore JNK activity to normal condition." (PMID 31562358, 2019).
systemic lupus erythematosus (2 papers, 2019 to 2025). An autoimmune multi-organ disease typically associated with vasculopathy and autoantibody production. "For JUN, the high-risk group was enriched in the "Hedgehog signaling pathway", "selenium amino acid metabolism", "TGF-beta signaling pathway", and "tyrosine metabolism", whereas the low-risk group was enriched in "allograft rejection" and "systemic lupus erythematosus"." (PMID 40092686, 2025).
thyroid (2 papers, 2025). "In the comparison between PTC and benign thyroid samples, SFN and CCNA1 were significantly upregulated, whereas FOS, HSPA5, JUN, CREB1, and MAP2K6 exhibited significant downregulation, supporting the findings obtained from the RT-qPCR analysis." (PMID 40722651, 2025).
acne (1 paper, 2021). An inflammatory process of the sebaceous glands which is characterized by comedones, nodules, papules and/or pustules on the skin. "Adapalene is a retinoid that acts as a comedolytic and anti-inflammatory agent that has been widely used due to its milder effects compared to those of other substances of the same class, mainly used for acne treatment that targets c-JUN via the AP-1 transcription factor." (PMID 34668739, 2021).
adrenal adenomas (1 paper, 2025). "•Oxidative stress drives spatial activation of FOS and JUN in peritumoral cortex of functional adrenal adenomas." (PMID 41412035, 2025). "In contrast, both total and phosphorylated forms of FOS and JUN were undetectable in normal adrenal cortex, as well as in both the tumor and adjacent cortex of non-functioning adrenal incidentalomas." (PMID 41412035, 2025).
adrenal tumors (1 paper, 2025). "•FOS and JUN couple redox imbalance with remodeling of adrenal tumor microenvironment." (PMID 41412035, 2025).
aneurysm (1 paper, 2022). Bulging or ballooning in an area of an artery secondary to arterial wall weakening. "Among them, six hub genes might be the core genes for the rupture of aneurysms, including APP, JUN, GSK3B,ErbB2, PPBP and THBS1." (PMID 35432454, 2022).
autoimmune hepatitis (1 paper, 2022). Hepatitis caused by autoantibodies. "Thus, the key target genes for autoimmune hepatitis treatment mainly included AKT1, IL6, VEGFA, CASP3, JUN, MYC, etc.." (PMID 36558908, 2022).
behavioral disorders (1 paper, 2017). "SNPs that disrupt binding also contribute to disease, an example of this form of regulatory perturbation being the loss of the emergent JUN•ATF3-binding site that is associated with Alzheimer’s and other neurological, cognitive and behavioral disorders." (PMID 28186491, 2017).
bladder tumor (1 paper, 2024). "JUN has been implicated in APF-mediated growth inhibition of bladder tumor cells and is a potential target of APF in patients with invasive BLCA68, and overexpression of JUN protein is also closely associated with the invasive growth of BLCA69." (PMID 38714855, 2024).
cervical adenocarcinoma (1 paper, 2025). An adenocarcinoma arising from the cervical epithelium. "We can hypothesize that the discrepancy with our results might depend on tissue-specific mechanisms employed by gastric cells, since we observed the phenomenon of JUN phosphorylation in bronchial epithelial (16HBE14o-) and cervical adenocarcinoma cells (HeLa)." (PMID 40507959, 2025).
chronic gastritis (1 paper, 2018). Inflammation of the stomach that is chronic in nature. "It seems that JUN and FOS are the two critical genes related to the chronic gastritis." (PMID 30425814, 2018).
ciliopathy (1 paper, 2022). A genetic disorder of the cellular cilia or the cilia anchoring structures, the basal bodies, or of ciliary function. "The targets of CREBP1 found from among the genes shared between the HLHS and ciliopathy interactomes were EP300, PRNP, SMAD3, SUMO1 and TBX6, while the targets of ALX4 were JUN and TCF7L2." (PMID 35456433, 2022).
coagulopathy (1 paper, 2025). "The involvement of JUN, FOXO1, and MAPK3 in complement and coagulation cascades suggests their potential role in immune-mediated inflammation and coagulopathy, which are frequently observed in HIV-infected individuals." (PMID 40574839, 2025).
corneal disease (1 paper, 2023). "FOSL1, along with FOSL2, a novel candidate for corneal disease in our study, and other TFs from the FOS and JUN families, are known to be important in epidermal cells." (PMID 37856539, 2023).
duodenal tumour (1 paper, 2022). "Additionally, activated c‐JUN promotes the epithelial–mesenchymal transformation of duodenal tumour cells by upregulating the expression of VIM to enhance their invasion and migration abilities, resulting in tumour progression." (PMID 36178086, 2022).
Dysmenorrhea (1 paper, 2013). Pain during menstruation that interferes with daily activities. "As SWT was also reported to have a significant therapeutic effect on dysmenorrhea, we proposed that SWT may play its therapeutic role on dysmenorrhea by targeting FOS and JUN to regulate the signaling pathway of pain." (PMID 24223693, 2013).
endocervical carcinoma (1 paper, 2019). A carcinoma that arises from epithelial cells of the endocervix. "To address the possible role of JUN in CC, we analysed the cervical and endocervical cancers dataset of The Cancer Genome Atlas (TCGA) and found that the expression of JUN was also significantly down-regulated in CC tissues compared with that in normal tissues." (PMID 30922331, 2019).
food allergy (1 paper, 2024). Gastrointestinal disturbances, skin eruptions, or shock due to allergic reactions to allergens in food. "A sensitization assay of sodium sulfite, which has been reported to induce food allergy, also showed a more than 3-fold increase in the expression level of the JUN gene." (PMID 39727897, 2024).
Gaucher disease (1 paper, 2021). Gaucher disease (GD) is a lysosomal storage disorder encompassing three main forms (types 1, 2 and 3), a fetal form and a variant with cardiac involvement (Gaucher disease - ophthalmoplegia - cardiovascular calcification or Gaucher-like disease). "We found numerous transcription factors that are putative regulators of cytokine expression in a cell-specific context, such as the signaling axes controlled by STAT2, JUN, and NR4A2 as candidate regulators of the monocyte Gaucher disease cytokine network." (PMID 34490253, 2021).
heroin dependence (1 paper, 2016). Physical and psychological dependence on the drug heroin. "Our classification analysis identified JUN, CEBPG, ENO2, and PRKCB as the key gene expression signatures for a subdivision of heroin dependence and controls." (PMID 27495086, 2016). "In this analysis, we found that the 4-gene model that contained JUN, CEBPB, ENO2, and PRKCB genes had an accuracy rate of 85.5% in the prediction of heroin addiction in this dataset." (PMID 27495086, 2016).
human papillomavirus infection (1 paper, 2024). "The TNF, VEGFA, JUN, and IGF-1 genes and neuron death, PI3K-Akt, and human papillomavirus infection signalling pathways may possibly explain this association." (PMID 38977982, 2024). "The TNF, VEGFA, JUN, and IGF-1 genes and the neuron death, PI3K-Akt, and human papillomavirus infection signalling pathways may possibly explain this association." (PMID 38977982, 2024).
iron overload (1 paper, 2023). "We conclude that JUN and ZFP36 could be the potential target genes to attenuate iron overload in patients with OA." (PMID 37741987, 2023).
leukopenia (1 paper, 2024). "Furthermore, JUN and FOS were identified as key regulators in multiple pathways related to leukopenia treatment." (PMID 39295929, 2024). "Transcriptomics results showed changes in the expression of JUN, FOS, and HGF genes in both the model group and the QJSB group, further supporting the potential role of QJSB in regulating cell growth processes for the treatment of leukopenia." (PMID 39295929, 2024). "Interestingly, multiple pathways involved in JUN and FOS may be key genes for QJSB in the treatment of leukopenia." (PMID 39295929, 2024). "Notably, AKT1, EGFR, IL6, STAT3, BCL2, CASP3, and JUN were identified as the top seven targets (degree >80) and may be key targets of QJSB in treating leukopenia." (PMID 39295929, 2024).
malignant mesothelioma (1 paper, 2013). A malignant neoplasm of the pleura or peritoneum, arising from mesothelial cells. "miRNA-615-3p dysregulates CDKN2A, NF2 and JUN in malignant mesothelioma and enhances the phagocytic capacity of splenic macrophages." (PMID 23387986, 2013).
malnutrition (1 paper, 2022). Inadequate nutrition resulting from poor diet, malabsorption, or abnormal nutrient distribution. "Based on these results, we selected JUN as a representative gene and focused on cancer types with co-occurring malnutrition to explore the association between them." (PMID 36091226, 2022). "A study using an animal model of prolonged fasting malnutrition showed that metabolic control in metabolically active organs is exerted by transcription factors, including JUN, activated by nutritional signaling." (PMID 36091226, 2022).
mastitis (1 paper, 2021). Inflammation of breast tissue during lactation or postpartum due to an obstructed duct or infection.
metastatic prostate carcinoma (1 paper, 2016). A carcinoma that arises from the prostate gland and has spread to other anatomic sites. "Among these elements are two TFs (PGR and HOXD10) in the primary and three TFs (STAT3, JUN and JUNB) in the metastatic prostate cancer network." (PMID 28005952, 2016).
myelofibrosis (1 paper, 2022). A partial or complete replacement of the bone marrow stroma by fibrous tissue. "Another prior report also found activation of noncanonical TGF-β signaling, including JUN, in patients with myelofibrosis." (PMID 35439167, 2022).
Noonan syndrome (1 paper, 2018). Noonan Syndrome (NS) is characterized by short stature, typical facial dysmorphism and congenital heart defects. "Gene sets in protein phosphorylation and JUN-MAPK (mitogen-activated protein kinase) cascades were also enriched but not entirely due to three Noonan syndrome genes (PTPN11, BRAF, RAF1)." (PMID 30532227, 2018).
oropharyngeal squamous cell carcinoma (1 paper, 2018). "Based on the original data of Rickman’s work published in 2008 in Oncogene, we compared JUN expression in oropharyngeal squamous cell carcinoma in patients without metastatic events at 5 years with that of patients with metastatic events at 5 years." (PMID 30459815, 2018). "Metastatic oropharyngeal squamous cell carcinoma had 1.69-fold higher JUN gene expression than non-metastatic oropharyngeal squamous cell carcinoma (p = 0.025)." (PMID 30459815, 2018).
Ovarian cyst (1 paper, 2021). The presence of one or more cysts of the ovary. "Jingshu granules could be used for ovarian cyst treatment by targeting JUN in the GnRH signaling pathway." (PMID 33623786, 2021).
periodontal disease (1 paper, 2024). "An overexpression of CTNNB1, FOS, JUN, GRB2, PIK3CA, and PIK3R1 may affect the cell cycle, resulting in excessive cell proliferation, and malignant transformation, besides being related to periodontal disease development and progression." (PMID 39517401, 2024).
polycystic ovary syndrome (1 paper, 2021). A disorder that manifests as multiple cysts on the ovaries. "It is noted that JUN has been identified as a potential key regulator in the development of polycystic ovary syndrome." (PMID 33623786, 2021). "Furthermore, decreased levels of p-c-JUN have been found in the ovary tissues of polycystic ovary syndrome rats." (PMID 33623786, 2021).
prostate (1 paper, 2025). "A previous study indicated that finasteride could potentially inhibit the expression of Insulin-like Growth Factor 1(IGF-1) by suppressing the activity of c-JUN within fibroblasts in benign prostate tissue, leading to a reduction in the synthesis and secretion of IGF-1." (PMID 39944628, 2025).
Pruritus (1 paper, 2024). Pruritus is an itch or a sensation that makes a person want to scratch. "Clearly, some genes such as AKT1, ALB, BCL2, STAT3, JUN, ESR1, and TNF hold important positions within the network, indicating their strong relevance to the pathogenesis of pruritus and their potential as key targets for drug intervention." (PMID 39606625, 2024).
pulmonary hypertension (1 paper, 2024). Increased pressure within the pulmonary circulation due to lung or heart disorder. "In addition, among the DEGs involved in the hypoxic pathway in IPAH, the expression of CAV1, JUN, and PDGFB, which promote the progression of pulmonary hypertension, were all increased." (PMID 38586587, 2024).
pulpitis (1 paper, 2021). Inflammation of the dental pulp. "Six transcription factors (i.e., GATA2, ETS1, FOXP3, STAT1, FOS, and JUN) were identified to play pivotal roles in pulpitis." (PMID 33777260, 2021). "Several transcription factors have been identified to be involved in the TF-gene regulatory network of pulpitis, including GATA2, ETS1, FOXP3, STAT1, FOS, and JUN." (PMID 33777260, 2021).
rheumatic diseases (1 paper, 2019). "Based on the reasonable assumption that JUN and FOS family proteins influence the development/progression of rheumatic diseases, the distribution of functionally relevant SNPs in the promoters of these proto-oncogenes and their potential association with RA or knee-OA were analysed." (PMID 30893847, 2019). "Therefore, the aim of this study was to analyse SNPs in the core promoters of the proto-oncogenes JUN, JUNB, JUND, and FOS in patients with rheumatic diseases, to investigate their functional relevance, and to assess potential associations between these SNPs and the occurrence of RA or knee-OA." (PMID 30893847, 2019).
rosacea (1 paper, 2021). A chronic erythematous skin disorder that affects the face. "Our results were consistent with the hypothesis that AP1 TFs (FOS, FOSB, JUN and JUND) were downregulated in rosacea lesions." (PMID 34290700, 2021).
RSV bronchiolitis (1 paper, 2017). "Single nucleotide polymorphisms in JUN has been associated with susceptibility of children to RSV bronchiolitis." (PMID 28877226, 2017).
skin sensitization (1 paper, 2024). An immunological response to previous exposure to a substance which results in an inflammatory skin reaction. "In terms of skin sensitization, JUN is implicated in the cellular response to sensitizers through its role in the regulation of inflammatory and immune responses." (PMID 39727897, 2024). "Although the specific pathways through which JUN contributes to skin sensitization are not fully elucidated, its involvement in the broader context of immune and inflammatory responses supports its relevance as a marker." (PMID 39727897, 2024).